LEP (leptin)
Diseases named in the same sentence as LEP in open-access papers (continued):
Sharing a sentence is not in itself a finding about the gene and the disease.
ischemic stroke (23 papers, 2011 to 2026). A stroke disorder caused by obstruction of blood flow to the brain, due to thrombotic (local blood clot formation) or embolic (due to a blood clot or other material traveling from another site) event. "Higher levels of leptin, IL1ra, and adrenomedullin were associated with increased ischemic stroke risk." (PMID 36691017, 2023). "Previous preclinical and clinical studies investigated the principle sex hormones, as well as select adipose-derived hormones (adiponectin, leptin, and ghrelin), as risk factors or potential treatments for ischemic stroke." (PMID 31412946, 2019). "A second case-control study enrolled post-menopausal women who had experienced an ischemic stroke and assessed the association with three plasma-based adipokines: adiponectin, leptin, and resistin." (PMID 31127075, 2019). "It is suggested that leptin can be considered a biomarker of ischemic stroke risk in the group of MetS patients." (PMID 29225622, 2017). "Several experimental studies have shown that an increased level of leptin has a proinflammatory potential and is associated with systemic atherosclerosis, coronary heart disease, and ischemic stroke." (PMID 29225622, 2017). "This method revealed strong evidence for the dependence of FA-related risk of ischemic stroke on leptin levels." (PMID 29225622, 2017). "In ischemic stroke patients intracerebral LEP deficiency caused by leptin resistance can trigger atherosclerotic/inflammatory vascular changes and vascular stiffness." (PMID 26783391, 2015). "However, a causal relationship between elevated leptin levels in the circulation and ischemic stroke events is still debatable." (PMID 35015765, 2022). "Leptin, a hormone that is predominantly produced by adipose tissue and one that links visceral obesity with MetS, may be a good risk marker for cardiovascular diseases, including ischemic stroke." (PMID 29225622, 2017). "Our study demonstrates the inhibition of the Fas–FasL interaction by systemically delivering a leptin-PEG-Fas-blocking peptide to brain regions affected by ischemic stroke." (PMID 38203830, 2024). "The pro-survival actions of leptin extend to several other forms of CNS-driven disease, as there is good evidence to support the protective effects of leptin in various models of ischaemic stroke." (PMID 39000459, 2024). "This study underscores the potential of precise molecular interventions in treating ischemic stroke and introduces a novel approach by utilizing a leptin-derived peptide for the targeted brain delivery of FBP." (PMID 38203830, 2024). "Few works are currently available regarding the correlation of leptin values ​​with outcomes following ischemic stroke." (PMID 36745280, 2023). "Despite the promising role of leptin in improving outcomes following experimental ischemic stroke, to date investigations on its potential therapeutic role in patients are still missing." (PMID 36745280, 2023). "A peak in serum levels of leptin and leptin/adiponectin ratio >1.16 has been observed 1 day after ischemic stroke and predicted poor functional outcomes measured using mRS after 3 months." (PMID 36699006, 2022). "When further examination of the subtypes of ischemic strokes was performed, we found that these higher serum leptin levels are primarily observed in the cardioembolic AIS patients with coexisting MetS." (PMID 29225622, 2017). "Specifically designed studies are needed to elucidate the role of leptin in MetS and FA-related ischemic stroke." (PMID 29225622, 2017). "Several studies have investigated and found an association between elevated leptin levels and unfavourable outcome in cerebral emergencies such as ICH, ischemic stroke and SAH." (PMID 27350906, 2016). "To date, no studies have investigated the relationship between HBOT and endogenous leptin in ischemic stroke models." (PMID 23510433, 2013). "Among all hormones modulated with HBOT, leptin is a promising candidate for the treatment of ischemic stroke." (PMID 23510433, 2013).
ischemic stroke (continued). "In addition to delivery, our study investigated the therapeutic impact of leptin-PEG-FBP on brain cell death in ischemic stroke." (PMID 38203830, 2024). "Among the various potential biomarkers, resistin and leptin, two adipokines involved in inflammation, metabolism and cardiovascular homeostasis, have emerged as candidates of particular interest in the context of ischemic stroke." (PMID 39336454, 2024). "The success of leptin-mediated transcytosis in delivering the FBP peptide underscores its potential as a therapeutic strategy for attenuating brain cell death in the context of ischemic stroke." (PMID 38203830, 2024). "The NIHSS score, the proportion receiving rehabilitation training, and the levels of IL-11, triglyceride (TG), and high-density leptin cholesterol (HDLC) of ischemic stroke patients in the mRS score ≥ 3 group were remarkably elevated than that in the mRS score ≤ 2 group." (PMID 36875689, 2023). "Leptin functions as a neuroprotective agent against ischemic neuronal injury, while it has been suggested that adiponectin increases to counteract the systemic inflammation conditions observed in ischemic stroke." (PMID 36699006, 2022). "LEP was demonstrated to exhibit neuroprotective effects against ischemic stroke." (PMID 26783391, 2015). "Adipocytokines leptin and adiponectin are associated with the incidence, progressionand outcome of atherosclerotic diseases, although previous studies have providedcontrasting results about differential plasma concentrations of the adipocytokinesin CAD, ischemic stroke and AD." (PMID 21633502, 2011). "Increased leptin levels have been reported in patients with intracerebral haematomas (ICH), SAH and ischemic stroke." (PMID 27350906, 2016). "In general, leptin protects against the mitochondrial oxidative stress induced in the rat MCAO model, suggesting that it represents a potential therapeutic drug in the treatment of ischemic stroke." (PMID 30632310, 2019). "The analysis of the AIS group showed that patients with ischemic stroke with accompanying MetS exhibited a much higher serum leptin concentration than MetS negative patients." (PMID 29225622, 2017).
Nephropathy (23 papers, 2014 to 2025). A nonspecific term referring to disease or damage of the kidneys. "The results of the Olivetti Heart Study, a recent prospective trial with a long-term follow-up, supports a key causal role of leptin on kidney damage." (PMID 32983895, 2020). "High serum leptin levels were observed in the early stages of kidney disease in T2DM patients, demonstrating that leptin degradation is already impaired in the early stages of nephropathy." (PMID 32130282, 2020). "All of these detrimental features of renal endotoxemia-induced damage were also decreased by leptin administration, as indicated by a blindly scored grading scale for kidney damage." (PMID 30618812, 2018). "Within the context of nephropathy, adipokines, such as leptin, resistin, visfatin and chemerin, have their serum levels markedly correlated to the disorders observed in renal diseases." (PMID 30126255, 2018). "This was probably due to the lack of any correlation between MEL and LEP in the AD animal, and to LEP not experiencing any concentration variations in the AD animal because of an important loss of weight induced by hyperlipidemic nephropathy." (PMID 24852173, 2014). "However, there are signs that kidney damage might be induced by endocrine activity of the adipose tissue via production of leptin." (PMID 38627329, 2024). "On the contrary, an independent study reported significantly reduced leptin levels in serum of Egyptian FM women compared with controls and researches on animal models of nephropathies suggested that leptin may exert neuroprotective activity and bring pain relief." (PMID 32582603, 2020). "On the other hand, some studies have demonstrated that there was no variation in leptin levels between diabetic individuals with and without nephropathy." (PMID 41150807, 2025). "Elevated leptin levels correspond to atherosclerosis and neuropathy but not diabetic retino- and nephropathy." (PMID 32443588, 2020).
hypoadiponectinemia (22 papers, 2007 to 2025). "Hypoadiponectinemia and hyperleptinemia are observed in both adults and children with obesity, and the adiponectin/leptin (Adipo/Lep) ratio has been proposed as a sensitive MetS marker in children and adolescents." (PMID 36920931, 2023). "It was pointed out that hypoadiponectinemia and higher levels of serum leptin commonly occurred in NASH patients." (PMID 35270077, 2022). "Hyperleptinemia ( i.e.where leptin is >5.6 ng/mL in males or >11.1 ng/mL in females) was observed in 66.96% of the participants and hypoadiponectinemia ( i.e.where adiponectin is <5 μg/mL) was observed in 44.35% of the participants." (PMID 29890036, 2018). "Prospectively, in adults, hypoadiponectinemia, decreased HMW adiponectin and increased leptin concentrations were differently reported as independent predictors of T2D development and, less consistently, of CHD events." (PMID 21365005, 2011).
tuberculosis (22 papers, 2006 to 2024). A chronic, recurrent infection caused by the bacterium Mycobacterium tuberculosis. "Weight loss in tuberculosis patients may also be associated with decreased plasma leptin levels in the host." (PMID 36506012, 2022). "In conclusion, leptin release is suppressed in tuberculosis andprobably low leptin concentrations may contribute to the increasedinfection susceptibility and recovery with sequelelesions in patients with tuberculosis." (PMID 17497033, 2007). "Previous studies on the relationship between plasma leptin and sarcoidosis or tuberculosis have been controversial." (PMID 26368286, 2015). "The concentrations of serum ICAM-1 and leptin obtained from the ELISA analysis were used to establish ROC curves to identify sarcoidosis (n = 89) and tuberculosis (n = 89)." (PMID 26368286, 2015). "Intercellular Adhesion Molecule 1(ICAM-1) and leptin were screened for differentially expressed proteins relevant to sarcoidosis and tuberculosis." (PMID 26368286, 2015). "For the first time, our study evaluated the potential of evaluating leptin and sICAM-1 for clinical diagnosis and determined the cutoff values of these targets for the differential diagnosis of sarcoidosis and tuberculosis." (PMID 26368286, 2015). "Within tuberculosis patients the BMI and leptin levels were positively correlated and decreased with increasing disease severity, whereas higher concentrations of IL-6, CRP, IL-1β, cortisol, and ghrelin were seen in cases with moderate to severe tuberculosis." (PMID 22022605, 2011). "Curiously, Yüksel and colleagues reported that serum leptin levels were higher among active tuberculosis patients compared to controls." (PMID 16942616, 2006). "However, the metabolic effects of leptin on infectious diseases, for example tuberculosis (TB), are still little known." (PMID 35933481, 2022). "Nevertheless, our study was much more hypothesis-generating than designed to answer key mechanistic questions on the roles of RAGE/leptin in tuberculosis and the use of sRAGE/leptin as a reliable prognostic tool in tuberculosis." (PMID 34214138, 2021). "Furthermore, plasma leptin levels were positively associated with the basal in vitro IFN-γ production and the ConA-driven proliferation of cells from tuberculosis patients." (PMID 22022605, 2011). "Leptin-deficient mice show reduced lung IFN-γ levels and greater susceptibility to M. tuberculosis compared with wild-type mice, and the levels of leptin were shown to be lower in TB patients than control subjects." (PMID 25295870, 2014). "Moreover, leptin-deficient mice are more susceptible to M. tuberculosis than wild-type mice, and T cell numbers, including those producing IFN-γ, are reduced in infected lungs, suggesting that leptin contributes to protection against tuberculosis." (PMID 23565890, 2013). "ICAM-1 and leptin were found to be potential markers for the diagnosis of sarcoidosis and differential diagnosis of sarcoidosis and sputum-negative tuberculosis." (PMID 26368286, 2015). "For this reason, we have decided to investigate therole of leptin and TNF-α in tuberculosis." (PMID 17497033, 2007). "We identified 2 differentially expressed proteins, leptin and ICAM-1, for the differential diagnosis of sarcoidosis and sputum-negative tuberculosis." (PMID 26368286, 2015).
amenorrhea (21 papers, 2013 to 2026). The absence of menses in a woman who has achieved reproductive age. "Leptin, secreted by adipose tissue, is necessary for GnRH pulsatility; low levels disrupt gonadotropin release, causing anovulation and amenorrhoea." (PMID 41209456, 2025). "There is evidence that in patients with AN, low body weight is related to a decrease in body fat, which, in turn, is associated with abnormal levels of gonadal hormones and leptin levels causing amenorrhea." (PMID 35406009, 2022). "Studies investigating weight loss in these athletes have shown that low EA may suppress leptin, triiodothyronine (T3), testosterone, and estradiol concentrations, and increase the incidence of menstrual irregularities, including amenorrhea markers of immunosuppression, and adaptive thermogenesis." (PMID 36678253, 2023). "On the other hand, excess adipose tissue loss that induces low or effectively deficient leptin levels can lead to hypogonadotropic hypogonadism (amenorrhea) that is partially reversed with leptin replacement." (PMID 41268722, 2026). "Our analyses confirmed that maternal obesity is associated with a significant reduction in adiponectin levels and elevated leptin and visfatin levels at both mid-pregnancy (18–22 weeks of amenorrhea) and at delivery." (PMID 40427500, 2025). "Leptin levels decrease in response to starvation, leading to lower estradiol levels and amenorrhea, further compounded by low fat storage in athletic women, potentially impacting bone density." (PMID 39595594, 2024). "Previous studies have shown decreased insulin, free T3, and leptin are associated with LEA and amenorrhea, while the results for free T4 and TSH are variable." (PMID 37342913, 2023). "This is important as recovery of leptin can in itself restore, for instance, ovulatory menstrual cycles and improve levels of reproductive and thyroid hormones as well as bone markers in amenorrhea." (PMID 28119632, 2016). "Additionally, individuals with eating disorders, amenorrhea and anorexia nervosa, exhibit a decrease in ghrelin and an increase in leptin once energy balance is achieved or after weight regain." (PMID 39595594, 2024). "Leptin administration to prepubertal female mice has a permissive action in accelerating the onset of puberty, further highlighting the important linkage between leptin and neuroendocrine function, and repletion of leptin restored menstrual cycles in women with hypoleptinemic amenorrhea." (PMID 38165042, 2024). "We have previously shown that restrictive and long-term dieting may suppress leptin, triiodothyronine (T3), testosterone, and estradiol concentrations and increase the incidence of menstrual irregularities, including amenorrhea." (PMID 36678253, 2023). "Energy deficits lead to hormonal changes, including decreased insulin-like growth factor-1 (IGF-1), growth hormone (GH) resistance, amenorrhoea, increased cortisol levels, and changes in hunger and satiety signalling (due to decreased levels of leptin, increased peptide YY, and ghrelin resistance)." (PMID 36401318, 2022). "Previous animal model studies reported that leptin, an anorexigen adipokine regulating LH pulsatility, gonadal function, puberty development and fertility, could participate in starvation-induced amenorrhea among AN patients." (PMID 30823566, 2019). "Leptin might also have a role in amenorrhea in AN, as it stimulates GnRH." (PMID 37630700, 2023). "Leptin values increased from the first control to discharge in Groups 0 (resumed menses) and 2 (no amenorrhea) (p value = 0.0054 and p value = 0.0104, respectively)." (PMID 37812282, 2024). "Hormones such as leptin, cortisol and prolactin do not seem to contribute the persistence of amenorrhea after weight normalization." (PMID 37773179, 2023). "On the other hand, Participant 1 with long-term amenorrhea gained minimal fat mass and showed no increase in leptin concentration during the first 6 months of the intervention despite an increase in circulating TT3." (PMID 23914797, 2013).
amenorrhea (continued). "However, the persistence of amenorrhea is not uncommon in women who have regained weight, regardless of the normalization of leptin levels." (PMID 37812282, 2024). "Negative energy balance leads to decreased leptin, amenorrhea, and subfertility, and leptin administration in women with hypothalamic amenorrhea is sufficient to restore their menses and fertility, raise serum estradiol, and increase the number of dominant follicles." (PMID 38131197, 2024).
multiple sclerosis (21 papers, 2013 to 2025). A progressive autoimmune disorder affecting the central nervous system resulting in demyelination. "Leptin, the main pro-inflammatory adipokine secreted by the adipose tissue, has been found increased in patients with multiple sclerosis and is able to regulate the immune system promoting a pro-inflammatory response." (PMID 40019662, 2025). "A previous study on multiple sclerosis also reported that CSF IL‐6 and CSF leptin levels were higher in obese patients." (PMID 39401137, 2024). "Leptin levels inversely correlated with regulatory T cell number in multiple sclerosis patients, and a direct link between leptin and regulatory T cell anergy was established." (PMID 32117323, 2020). "Moreover, circulating inflammatory adipokines, such as leptin, have been found in people with multiple sclerosis." (PMID 40019662, 2025). "Leptin signaling in both innate and adaptative immune cells might have immunomodulatory effects in the context of multiple sclerosis." (PMID 40019662, 2025). "Beyond T cell regulation, leptin exerts broad immunomodulatory effects by influencing macrophages and neutrophil activity and enhancing the expression of proinflammatory mediators that play a central role in the pathogenesis of neuroinflammatory disorders, including multiple sclerosis (MS)." (PMID 41516046, 2025). "Leptin and adipocyte-fatty acid binding protein (A-FABP) are produced by white adipose tissue and may play a role in chronic inflammation in Multiple Sclerosis (MS)." (PMID 24215402, 2013).